CAMK2G (calcium/calmodulin dependent protein kinase II gamma)
Description:
Calcium/calmodulin-dependent protein kinase that functions autonomously after Ca(2+)/calmodulin-binding and autophosphorylation, and is involved in sarcoplasmic reticulum Ca(2+) transport in skeletal muscle and may function in dendritic spine and synapse formation and neuronal plasticity. In slow-twitch muscles, is involved in regulation of sarcoplasmic reticulum (SR) Ca(2+) transport and in fast-twitch muscle participates in the control of Ca(2+) release from the SR through phosphorylation of the ryanodine receptor-coupling factor triadin. In the central nervous system, it is involved in the regulation of neurite formation and arborization. It may participate in the promotion of dendritic spine and synapse formation and maintenance of synaptic plasticity which enables long-term potentiation (LTP) and hippocampus-dependent learning. In response to interferon-gamma (IFN-gamma) stimulation, catalyzes phosphorylation of STAT1, stimulating the JAK-STAT signaling pathway (By similarity).
Synonyms: CAMK; CAMK-II; CAMKG; MRD59
Tractability: Small molecule: a structure with a bound ligand is known; a high-quality ligand is known; it has a high-quality binding pocket; it belongs to a druggable protein family. Antibody: UniProt places it where antibodies can reach, with high confidence; the Human Protein Atlas places it where antibodies can reach. PROTAC: ubiquitination databases record sites on it; its protein half-life has been measured; a small molecule that binds it is known.
Target class: CAMK protein kinase CAMK2 family; Protein Kinase; Enzyme; CAMK protein kinase group; Kinase
Gene: Protein-coding gene on chromosome 10 (73,812,501 to 73,874,641, reverse strand). Ensembl gene ENSG00000148660.
Subcellular location: Sarcoplasmic reticulum membrane
Subcellular location (Human Protein Atlas): Plasma membrane; Primary cilium tip; Primary cilium transition zone; Principal piece; Calyx; Cell Junctions; Connecting piece; End piece; Perinuclear theca
Pathways (Reactome):
Neuronal System: Assembly and cell surface presentation of NMDA receptors; CREB1 phosphorylation through the activation of CaMKII/CaMKK/CaMKIV cascasde; Long-term potentiation; Negative regulation of NMDA receptor-mediated neuronal transmission; Ras activation upon Ca2+ influx through NMDA receptor; Trafficking of AMPA receptors; Unblocking of NMDA receptors, glutamate binding and activation
Disease: Dengue Virus-Host Interactions; Paradoxical activation of RAF signaling by kinase inactive BRAF; Signaling by BRAF and RAF1 fusions; Signaling by RAF1 mutants; Signaling by moderate kinase activity BRAF mutants; Signaling downstream of RAS mutants
Signal Transduction: CaMK IV-mediated phosphorylation of CREB; RAF activation; RAF/MAP kinase cascade
Muscle contraction: Ion homeostasis; Phase 0 - rapid depolarisation
Cellular responses to stimuli: HSF1-dependent transactivation
Immune System: Interferon gamma signaling
Transport of small molecules: Ion transport by P-type ATPases
Gene Ontology:
Molecular function: identical protein binding; protein binding; protein homodimerization activity; calcium-dependent protein serine/threonine phosphatase activity; calcium/calmodulin-dependent protein kinase activity; calmodulin binding; protein serine kinase activity; ATP binding; protein kinase activity
Biological process: regulation of neuron projection development; insulin secretion; long-term synaptic potentiation; regulation of calcium ion transport; regulation of neuronal synaptic plasticity; regulation of protein localization to plasma membrane; regulation of skeletal muscle adaptation
Cellular component: calcium- and calmodulin-dependent protein kinase complex; membrane; cytoplasm; cytosol; endocytic vesicle membrane; endoplasmic reticulum membrane; neuron projection; nucleoplasm; postsynaptic density; sarcoplasmic reticulum membrane
Genetic constraint (gnomAD): Loss-of-function variants: 12 observed, 48.17 expected, observed/expected ratio (o/e) 0.25, 90% interval 0.16 to 0.4. The upper end of that interval is the gene's LOEUF score, 0.4, which puts it in group 1 of 6, group 1 being the genes least tolerant of losing a copy. Missense variants: 404 observed, 608.81 expected, observed/expected ratio (o/e) 0.66, 90% interval 0.61 to 0.72. Synonymous variants: 219 observed, 234.24 expected, observed/expected ratio (o/e) 0.93, 90% interval 0.84 to 1.05.
Gene-disease validity (ClinGen):
ClinGen rates the evidence that CAMK2G causes each of these diseases.
intellectual developmental disorder 59 (autosomal dominant): Limited.
Homologues: Orthologues: rat Camk2g (99% identical), mouse Camk2g (96% identical), dog CAMK2G (95% identical), pig CAMK2G (95% identical), macaque CAMK2G (94% identical), chimpanzee CAMK2G (92% identical), rabbit CAMK2G (90% identical), guinea pig CAMK2G (89% identical), tropical clawed frog camk2g (88% identical), zebrafish camk2g2 (85% identical), zebrafish camk2g1 (81% identical). Paralogues in human: CAMK2B (81% identical), CAMK2D (74% identical), CAMK2A (69% identical), CAMK1 (25% identical), CAMK1D (24% identical), CAMK1G (24% identical), DCLK2 (24% identical), DCLK1 (23% identical), PNCK (23% identical), PHKG2 (22% identical), PHKG1 (22% identical), CAMKK1 (20% identical), and 10 more.
Diseases named in the same sentence as CAMK2G in open-access papers:
CAMK2G is named in the same sentence as 311 diseases in open-access papers, as found by Europe PMC text mining. Sharing a sentence is not in itself a finding about the gene and the disease. The quoted sentences say what the papers report.
myocardial infarction (67 papers, 2009 to 2026). Gross necrosis of the myocardium, as a result of interruption of the blood supply to the area, as in coronary thrombosis. "In the box plot of GSE61144, CaMK2G expression was more significant in acute myocardial infarction than in normal myocardium." (PMID 35767566, 2022).
diabetes (53 papers, 2011 to 2025). "Functional analysis and lncRNA-mRNA network analysis showed that it contained many genes that have been reported to be related to diabetes and vascular diseases, such as TOMM5, MYLK, PDLIM1, and CAMK2G." (PMID 35508613, 2022). "The related genes such as TOMM5, and MYLK have been reported to have implications in diabetes, and PDLIM1 and CAMK2G were found to be related to atherosclerosis." (PMID 35508613, 2022).
Cognitive impairment (47 papers, 2011 to 2026). Abnormal cognition is characterized by deficits in thinking, reasoning, or remembering. "Meanwhile, loss of Camk2g function has been implicated in synaptic deficits and cognitive impairment." (PMID 41150532, 2025). "The concurrent downregulation of both Camk2a and Camk2g may therefore contribute to cognitive deficits associated with cerebellar dysfunction." (PMID 41150532, 2025).
ischemia (46 papers, 2013 to 2025). A hypoperfusion of the BLOOD through an organ or tissue caused by a PATHOLOGIC CONSTRICTION or obstruction of its BLOOD VESSELS, or an absence of BLOOD CIRCULATION. "Our data indicated that CAMK2D/CaMKIIδ and CAMK2G/CaMKIIγ were selectively upregulated in a time-dependent manner at both transcriptional and protein levels after acute ischemia." (PMID 29992531, 2019).
depression (35 papers, 2006 to 2025). "The correlation of Adcy9, Apc, Camk2b, Camk2g, and Ctnnd2 with the pathological mechanisms of depression was first reported in the present work." (PMID 34520625, 2021).
breast carcinoma (28 papers, 2011 to 2026). "We next assessed whether CaMKII expression is associated with breast cancer patient outcome by examining CAMK2A, CAMK2B, CAMK2G and CAMK2D mRNA expression in a publically available 1881-sample breast cancer data set25." (PMID 27605043, 2016).
glioma (24 papers, 2015 to 2025). A benign or malignant brain and spinal cord tumor that arises from glial cells (astrocytes, oligodendrocytes, ependymal cells). "In GBM-glioma subtype the order of expression from highest to lowest was as follows: CaMK2G > CaMK2B ≥ CaMK2A > CaMK2D." (PMID 28663722, 2017). "Consistently, the hyperphosphorylation of microtubule‐associated proteins (MAP2 and MAP1B) revealed the activation of CAMK2G, GSK3A, GSK3B, MAPK8, and MAP4K6, corresponding to the active MAPK signaling pathway in glioma." (PMID 39716938, 2025).
dilated cardiomyopathy (20 papers, 2009 to 2025). Cardiomyopathy which is characterized by dilation and contractile dysfunction of the left and right ventricles. "The common JAGs responsible for heart diseases included: JARID2 and TBX20, associated with a structural heart anomaly; JAZF1, associated with cardiac tumors; CAMK2G, associated with conduction defects; and CMAK2D and TMPO, associated with dilated cardiomyopathy." (PMID 29449671, 2018).
schizophrenia (19 papers, 2008 to 2025). A major psychotic disorder characterized by abnormalities in the perception or expression of reality. "Interestingly, knockdown of H2A.Z.1, but not H2A.Z.2, led to altered expression of several candidate genes linked to psychiatric disorders such as autism and schizophrenia (Neurexin1, Shank3, CaMK2G, Vamp7, Gsk3b, Tuba8, Grm8, etc.)." (PMID 28856239, 2017).
neuroblastoma (17 papers, 2008 to 2025). Neuroblastoma (NB) is the most common solid, extracranial childhood tumor. "In neuroblastoma, high CAMK2G expression correlates with favorable prognosis and neuronal differentiation, whereas its loss promotes proliferation and invasion." (PMID 41331166, 2025).
lung carcinoma (11 papers, 2015 to 2025). "While microarray data quoted in this study showed a more consistent survival significance of CAMK2A than CAMK2G in lung cancer, more studies would help to clarify their respective roles." (PMID 32483123, 2020).
type 2 diabetes (11 papers, 2013 to 2026). "In this study, we obtained CaMK2G and PPP1CA, genes associated with the CaMKII pathway and type 2 diabetes and acute cardiovascular events, by integrative gene analysis and validated their expression in the relevant dataset." (PMID 35767566, 2022). "We also derived that Empagliflozin acts on amino acid TRP-125 of CaMK2G gene and GLN-249 ASP-210 ASP-208 of PPP1CA through CaMKII pathway, thus acting on type 2 diabetes and acute cardiovascular events by molecular docking technique." (PMID 35767566, 2022). "The present study obtained CaMK2G and PPP1CA, a gene associated with the CaMKII pathway and type 2 diabetes and acute cardiovascular events, by integrative gene analysis." (PMID 35767566, 2022). "Recent findings suggest that Camk2g involved in the regulation of calcium in the islet beta cells is a candidate gene for type 2 diabetes." (PMID 23555558, 2013).
diabetic cardiomyopathy (9 papers, 2021 to 2024). Diabetic cardiomyopathy is a disorder of the heart muscle in people with diabetes. "We concluded that CaMK2G and PPP1CA are associated with the CaMKII pathway and diabetic cardiomyopathy." (PMID 35767566, 2022).
atherosclerosis (8 papers, 2019 to 2026). A disease characterized by the build-up of fatty material and calcium deposition in the arterial wall resulting in partial or complete occlusion of the arterial lumen. "Utilizing bulk RNA sequencing, six core efferocytosis-related genes (STAB1, ANO5, GULP1, LGR6, SCARF1, and CAMK2G) were identified, which exhibit significant diagnostic potential in atherosclerosis." (PMID 42272635, 2026). "Mer-mediated efferocytosis in atherosclerosis is prevented by macrophages that express calcium/calmodulin-dependent protein kinase II gamma (CaMKII-gamma)." (PMID 39684449, 2024). "Additionally, CD40, F11R, TNRC18, and calcium/calmodulin-dependent protein kinase type II gamma (CAMK2G) were screened out and validated using enzyme-linked immunosorbent assay (ELISA) in an independent patient cohort and immunohistochemical (IHC) staining in an atherosclerosis mouse model." (PMID 32714363, 2020).
dementia (8 papers, 2014 to 2022). Loss of intellectual abilities interfering with an individual's social and occupational functions. "For instance, CAMK2G and PDZD7 are involved in Usher Syndrome the most common condition leading to deafness and blindness, as well as DNMT1 has a role in DNMT1-Related Dementia, Deafness, and Sensory Neuropathy and LRTOMT in deafness." (PMID 28993790, 2017).
ischemic heart disease (5 papers, 2015 to 2024). "Other clinical studies have linked CAMK2G to coronary artery disease, altered calcium signaling and heart failure, underscoring its role in cardiac disease as well." (PMID 34162925, 2021). "CAMK2G was identified as an enhancer gene for coronary artery disease in a GWAS meta-analysis." (PMID 32719717, 2020).
cocaine addiction (3 papers, 2021 to 2023). "There were 13 genes enriched in cocaine addiction and the circadian entrainment signaling pathway (Bdnf, Gnai1, Gnai3, Grin2d, Grm2, Maob, Cam2, Camk2g, Gng12, Mapk1, Pcb4, Prkm2, and Pdyn)." (PMID 36164400, 2022).
COVID-19 (3 papers, 2021 to 2024). A disease caused by infection with severe acute respiratory syndrome coronavirus 2. "Four DEPs (RAC1, CAMK2G, DAAM1, and RAC2) were enriched in the noncanonical Wnt pathway and two DEPs (TLE3 and CACYBP) were enriched in the canonical pathway in the COVID-19 comparison group." (PMID 39301288, 2024).
E. coli (2 papers, 2016 to 2020). "Thus, EPS pretreatment can reduce the overexpression of PRKAR1A and CAMK2G, which are activated in E. coli infection." (PMID 32234079, 2020).
psoriasis (2 papers, 2009 to 2024). An autoimmune condition characterized by red, well-delineated plaques with silvery scales that are usually on the extensor surfaces and scalp. "Camk2g‐deficient mice exhibits attenuated imiquimod‐induced psoriasis‐like manifestations and skin inflammation." (PMID 38544478, 2024). "To identify psycho‐neurological factors that regulate the pathogenesis of psoriasis, we explored associations of neurogenic susceptibility gene CAMK2G expression with psoriasis in clinical samples and animal models." (PMID 38544478, 2024). "In the present study, we found that the susceptibility gene CAMK2G, which is mainly expressed in cutaneous sympathetic nerves, affected the progression of psoriasis by promoting γδT‐cells IL‐17 production through norepinephrine secretion." (PMID 38544478, 2024). "To determine whether increased CAMK2G expression in psoriasis is associated with SNS activation, we applied a tube restraint–induced acute stress model and found that acute stress indeed increased cutaneous Camk2g transcription." (PMID 38544478, 2024). "To directly evaluate the function of sympathetic nerve‐specific Camk2g in psoriasis, we generated a Camk2g gene conditional knockout mouse (Camk2gfl/flDat‐Cre)." (PMID 38544478, 2024). "Real‐time quantitative polymerase chain reaction (qPCR) showed that the Camk2g transcript level in skin was significantly higher in mice with IMQ‐induced psoriasis than in Vaseline (VAS)‐treated controls." (PMID 38544478, 2024). "Compared to IMQ‐treated WT mice, IMQ‐treated Camk2g–/– mice displayed significantly weakened psoriasis‐like manifestations, as indicated as reduced back skin thickness, mitigated erythema, and scaling." (PMID 38544478, 2024). "In an IMQ‐induced psoriasis model, Camk2g–/– mice exhibited significantly weakened psoriasis‐like manifestations and decreased γδT‐cell IL‐17A production relative to wild‐type (WT) mice." (PMID 38544478, 2024). "In IMQ‐treated mice, subcutaneous NE injection aggravated psoriasis‐like manifestations, eliminated the difference in skin thickness between WT and Camk2gfl/flDat‐Cre mice, increased the number of IL‐17A+ γδT cells in skin and rescued the Camk2g deletion–induced reduction of this number." (PMID 38544478, 2024). "The results suggest that CAMK2G and ADRB1 are targets for the clinical treatment of psoriasis, especially that affected by neuropsychiatric factors." (PMID 38544478, 2024).
cardioembolic stroke (1 paper, 2020). "We found that CAMK2G (P = 5.14E-07) was 1.3-fold upregulated in cardioembolic stroke compared to controls." (PMID 32719717, 2020).
esophageal adenocarcinoma (1 paper, 2024). A malignant tumor with glandular differentiation arising predominantly from Barrett mucosa in the lower third of the esophagus. "In esophageal adenocarcinomas, the USP54-encoding gene is sometimes fused with the CAMK2G-encoding gene." (PMID 38321455, 2024).
GM2 gangliosidosis (1 paper, 2019). A group of recessively inherited diseases characterized by the intralysosomal accumulation of G(M2) GANGLIOSIDE in the neuronal cells. "There is no direct evidence describing the role of CAMK2G in GM2 gangliosidosis." (PMID 31261761, 2019).
cancer (79 papers, 2008 to 2026). A tumor composed of atypical neoplastic, often pleomorphic cells that invade other tissues. "On the other hand, CAMK2G which is ubiquitously expressed has been shown to support cancers through activating transcription factors such as AKT1, CREB, CDK1/2." (PMID 32483123, 2020). "In our study, five DEPs (CD44, Stat3, CAMK2D, CAMK2B and CAMK2G) were identified in the proteoglycans in cancer signaling pathway, which worked together to modulate functions of this pathway, such as cell migration and invasion, cell adhesion, cell growth and survival." (PMID 36678534, 2022). "We did not detect cross-reactivity with SERPINB9 and CAMK2G, two potential candidates with relevance in human cancer." (PMID 30993208, 2019). "In addition, we identify CAMK2D and CAMK2G as downstream effectors of PEAK1 in TNBC and ‘repurposing’ of the second generation CAMK2 inhibitor RA306 as a potential therapeutic strategy against oncogenic PEAK1 signalling in poor prognosis human cancers such as TNBC." (PMID 39984440, 2025).
neurodevelopmental disorder (5 papers, 2021 to 2024). A behavioral and cognitive disorder with onset during the developmental period that involves impaired or aberrant development of intellectual, motor, or social functions. "With the identification of patients suffering from CAMK2G-associated neurodevelopmental disorder, the interest to study the role of CAMK2G in normal brain functioning significantly increased." (PMID 36685241, 2022). "The finding that a mutation in this gene causes a neurodevelopmental disorder suggests that CAMK2G plays an important role in neurodevelopment." (PMID 36685241, 2022). "The gamma subunit of calcium/calmodulin-dependent protein kinase 2 (CAMK2G) is expressed throughout the brain and is associated with neurodevelopmental disorders." (PMID 36685241, 2022). "Studying the role of CAMK2G in the brain has only recently become a focus of interest, amongst others due to the identification of patients with neurodevelopmental disorders carrying a mutation in the CAMK2G gene, highlighting the function of CAMK2G in normal brain functioning." (PMID 36685241, 2022).
CAMK2G also shares sentences with these, for which no sentence is quoted: heart failure (171 papers); cardiac hypertrophy (143); Arrhythmia (122); tumor (64); cardiac disease (62); Anxiety (55); Hyperglycemia (38); atrial fibrillation (35); cardiovascular diseases (33); Ventricular arrhythmia (33); cardiac arrhythmias (32); cardiomyopathy (31); Alzheimer disease (25); Hypertension (24); infection (23); memory impairment (23); Obesity (23); myocardial ischemia (22); Stroke (18); Cerebral ischemia (17); epilepsy (15); glioblastoma (14); ischemic stroke (13); prostate carcinoma (13); leukemia (12); melanoma (12); neurodegenerative disease (12); Sepsis (12); glaucoma (11); hypertrophy (11).
A further 256 diseases each share a sentence with CAMK2G in 10 papers or fewer.